TF (transferrin)
Diseases named in the same sentence as TF in open-access papers (continued):
Sharing a sentence is not in itself a finding about the gene and the disease.
iron deficiency (continued). "Low serum iron, reduced ferritin, low transferrin saturation (TSAT), and elevated transferrin levels are characteristic markers of iron deficiency." (PMID 41155502, 2025). "The early follicular phase, corresponding to menstruation, was characterized by the lowest serum iron, transferrin saturation (%TS), and body iron index (BII), along with the highest prevalence of iron deficiency (ID) and iron deficiency anemia (IDA)." (PMID 41362311, 2025). "Iron deficiency anemia (IDA) was diagnosed by hypochromic microcytic anemia and reduced transferrin saturation (<15%) and/or ferritin (<15 mg/L)." (PMID 40084341, 2025). "Developing reliable biomarkers for iron status remains challenging, as iron deficiency is marked by reduced Hb and ferritin-bound iron levels, increased TIBC, and low transferrin saturation." (PMID 40585667, 2025). "Transferrin saturation (TSAT) and ferritin are commonly used markers to assess iron deficiency in clinical practice." (PMID 40869365, 2025). "SI, TIBC, FE, TF, and HAMP are critical markers for evaluating and tracking iron deficiency and overload." (PMID 41198727, 2025). "While the CARD patients seemed to possess unaffected transferrin levels, all CKD patients showed progressing signs of functional iron deficiency (low TIBC, high ferritin)." (PMID 40002748, 2025). "TIBC reflects the total capacity of transferrin to bind iron, with elevated TIBC typically indicating a state of functional iron deficiency, wherein iron availability is limited despite normal or low iron stores." (PMID 41141252, 2025). "Current guidelines advocate for the frequent reassessment of ferritin and transferrin saturation (TSAT), particularly in individuals diagnosed with iron deficiency or those undergoing intravenous iron treatment." (PMID 40363966, 2025). "According to the 2021 ESC recommendations, all patients with HF should undergo routine full blood count, serum ferritin concentration, and transferrin saturation (TSAT) screening for anaemia and iron deficiency." (PMID 38965691, 2025). "According to NCCN criteria, absolute iron deficiency is defined as transferrin saturation (TSAT) <20% and serum ferritin <30 ng/mL, whereas functional iron deficiency is defined as TSAT <50% and ferritin between 30 and 500 ng/mL." (PMID 41287652, 2025). "Biochemistry also showed that patients with PPCM had iron deficiency (Fe 5.3 μmol/L [IQR 3.6–8.4], transferrin 2.4 mg/dl [IQR 2.3–3.2], transferrin saturation 8% [IQR 7.0–11.0] and ferritin 73.0 μg/L [IQR 51.0–88.0])." (PMID 40654268, 2025). "IDA, iron-deficiency anemia; TSAT, transferrin saturation; CHr, reticulocyte Hgb content; HRC%, percentage of hypochromic red blood cells; sTfR, soluble transferrin receptor; NGAL, neutrophil gelatinase-associated lipocalin." (PMID 39958087, 2025). "Transferrin saturation (iron concentration divided by TIBC) is mostly <20% in all the COVID-19 patients, which can support the presence of iron deficiency but can also be explained by inflammatory anemia." (PMID 38337670, 2024). "As literatures reported, microbial infections cause iron deficiency anemia (IDA) and IDA promotes transferrin expression." (PMID 38274126, 2024). "Since the tests used for the screening of iron deficiency, such as ferritin, transferrin, and TSAT are confounded by the presence of inflammation, iron deficiency diagnosis is challenging." (PMID 39000113, 2024). "Iron deficiency significantly decreased the FTH level at the protein level, even if transferrin-bound iron (serum) was freshly available for the cells." (PMID 37373063, 2023). "Lower iron conc., serum ferritin (SF), transferrin saturation, and TBIS, with higher levels of sTfR (nmol/L), were significantly (P = 0.001) reported in subjects with iron deficiency (ID)." (PMID 38102707, 2023). "During iron deficiency, DMT1–transferrin and ferritin–NCOA4 systems increase intracellular iron levels via endosomes and ferritinophagy, respectively." (PMID 37107292, 2023).
iron deficiency (continued). "Transferrin saturation <16%, which according to the ECCO guidelines indicates iron deficiency, was found in 13 patients with UC and 12 patients with CD and anaemia (p > 0.05)." (PMID 37048531, 2023). "In this study, patients were divided into “absolute iron deficiency”, “functional iron deficiency” and “other” (TSAT > 20%) groups according to ferritin and transferrin saturation." (PMID 37999123, 2023). "In this study, we investigated the association between LRG1 and several iron deficiency anemia markers, including hemoglobin (Hb), albumin, red cell distribution width (RDW), iron, ferritin, and Hb transferrin saturation." (PMID 37513518, 2023). "Serum iron and transferrin saturation are decreased, and RBC ZPP is increased in iron deficiency, although the latter also occurs in inflammatory disorders and due to exposure to lead." (PMID 37061792, 2023). "Iron transport markers, such as transferrin saturation, are impacted earlier in the process of iron depletion than is functional iron (e.g., hemoglobin), suggesting that non-pregnant women taking prescription opioids may have increased risk of mild iron deficiency." (PMID 37111110, 2023). "The linkage changes among transferrin, TIBC, and TSAT in response to HIF-PHI treatment in renal anemia are the opposite to the results in iron deficiency anemia after iron supplementation, reflecting the different mechanisms in these two anemia scenarios." (PMID 38099145, 2023). "Functional iron deficiency (FID) is defined as the presence of low circulating iron levels, low Transferrin Saturation (< 20%) and a normal or increased serum ferritin in the setting of systemic inflammation." (PMID 36709278, 2023). "According to the joint quartiles of baseline transferrin saturation and ferritin, iron status was categorized as reference iron status (RIS), absolute iron deficiency (AID), functional iron deficiency (FID), and high iron status (HIS)." (PMID 35458175, 2022). "Since transferrin is an acute-phase protein, its concentration decreases in response to cytokine production, and in contrast to the FID, absolute iron deficiency is diagnosed when transferrin values are normal and high." (PMID 36555993, 2022). "It has been shown that iron deficiency anemia (IDA) and the use of oral contraceptives can induce transferrin overexpression through hypoxia and estrogen response elements, respectively, thus promoting hypercoagulability." (PMID 35956000, 2022). "Diagnosis of iron deficiency anemia (IDA) relies on measurements of serum iron (SI), transferrin, transferrin saturation and ferritin in subjects with microcytic/hypochromic anemia." (PMID 35177695, 2022). "States of iron deficiency are also characterized by low iron levels, high transferrin/iron-binding capacity (TIBC), and low % transferrin saturation." (PMID 36139084, 2022). "In cancer patients, high ferritin >100 μg/L in combination with low transferrin saturation (TSAT) (<20%) is suggested as a criterion of FID, and ferritin <100 μg/L is a criterion of absolute iron deficiency (AID)." (PMID 36555993, 2022). "There were significant differences (p < 0.001) before and after correction of preoperative anaemia and/or iron deficiency with FCM in Hb, serum ferritin and transferrin saturation rate (TS)." (PMID 36369296, 2022). "The control group was characterised by a number of features of iron deficiency anaemia, including lower RBC, HGB, HCT and MCV, along with elevated transferrin." (PMID 35745183, 2022). "Additional tests such as serum ferritin, transferrin saturation, erythrocyte protoporphyrin, and C-reactive protein (CRP) are required to detect iron deficiency." (PMID 34496786, 2021). "Patients with absolute iron deficiency typically present with a decreased iron level, decreased ferritin level, elevated total iron binding capacity (TIBC), and decreased transferrin saturation (TSAT; calculated as serum iron/TIBC × 100%)." (PMID 33498292, 2021).
iron deficiency (continued). "In healthy persons with iron deficiency and iron deficiency anemia (IDA), serum hepcidin, ferritin, and transferrin saturation are significantly low." (PMID 33466578, 2021). "Low transferrin saturation (TSAT), calculated by serum iron divided by total iron-binding capacity (TIBC), indicates iron deficiency." (PMID 33863963, 2021). "Several parameters lead to diagnose systemic (serum ferritin, serum iron, serum transferrin, and transferrin saturation levels) and/or erythroid (serum transferrin receptor (sTfR) and erythrocyte protoporphyrin (PPIX)) iron deficiencies." (PMID 34444676, 2021). "Eleven SNPs had alleles that were clearly associated with low iron, iron deficiency anaemia and/or IRIDA (SNPs in TMPRSS6 (rs855791, rs2235321, rs2235324, rs4820268, rs2413450, rs228916, rs228918 and rs228921) and TF (rs3811647, rs1799899 and rs8177253)." (PMID 32609760, 2020). "In the liver, TFR2 expression is posttranscriptionally regulated by diferric transferrin; in erythroid cells in vitro, TFR2 is cleaved from the cell surface in iron deficiency." (PMID 29073189, 2017). "Plasma sTfR, transferrin, and UIBC, however, were higher during late pregnancy in the LNS groups, indicating iron deficiency and increased cellular iron demand." (PMID 28515164, 2017). "In this study GDF-15 was related hsCRP and NGAL (neutrophil gelatin associated lipocalin) in patients without functional iron deficiency, while in patients with functional iron deficiency, GDF-15 was related to serum iron and transferrin saturation." (PMID 27043030, 2016). "Transferrin and TIBC were significantly higher in female patients with IDA compared to female patients with iron deficiency." (PMID 24385778, 2013). "Whereas anemia of chronic disease is marked by elevated ferritin but reduced transferrin (and total iron-binding capacity (TIBC)) levels, iron deficiency anemia exhibits the reverse profile." (PMID 22871034, 2012). "Hepcidin levels are low in iron deficiency while FPN-1 on the basolateral membranes of duodenal enterocytes is increased to absorb and transfer iron to circulating transferrin." (PMID 20631898, 2010). "Biochemical analysis revealed significantly lower serum iron, ferritin, transferrin saturation, albumin, and prealbumin levels among anemic girls, alongside elevated total iron-binding capacity and CRP, indicating a predominance of iron deficiency anemia with an inflammatory component." (PMID 42232018, 2026). "Existing methods of diagnosing iron deficiency come with various problems; a transferrin saturation of <20% is the most popular, but it is not regarded as a perfect solution." (PMID 41753362, 2026). "TIBC is typically elevated in iron deficiency due to an increase in unbound transferrin while unsaturated iron-binding capacity (UIBC) represents the portion of transferrin that is not bound to iron, complementing TIBC in assessing iron-binding status." (PMID 40168317, 2025). "The presence of this association with transferrin, rather than ferritin, is likely due to its increased production in response to iron deficiency and reflects the actual lack of available iron in the body." (PMID 41029668, 2025). "It is important to note that people with iron deficiency without anemia who should be considered for treatment include those who have low ferritin levels or low transferrin saturation (TSAT), which is a known indicator of the availability of iron in the body." (PMID 40648893, 2025). "The absence of ferritin, transferrin saturation and hemoglobin data precludes distinction between iron-deficiency anemia, functional iron deficiency and anemia of chronic disease." (PMID 41340665, 2025). "Blood tests revealed iron deficiency without anaemia (ferritin 21 μg/L, transferrin saturation 15%, hemoglobin [Hb] 121 g/L)." (PMID 41158936, 2025).
iron deficiency (continued). "The iron-related biomarkers indicated a pattern of iron deficiency, including in non-anemic patients, with reduced % transferrin saturation (p < 0.01) and an elevated ceruloplasmin/transferrin ratio (p = 0.02)." (PMID 40507970, 2025). "In our patient’s case, the haematological profile (ferritin well above > 100 μg/L, mildly reduced transferrin saturation), most likely reflects functional rather than true iron deficiency." (PMID 40764527, 2025). "Laboratory tests showed iron deficiency without anaemia: haemoglobin: 121 g/L, haematocrit: 0.36, mean corpuscular volume: 82 fL, serum iron: 11.0 μmol/L, transferrin saturation: 15%, and ferritin: 21 μg/L." (PMID 41158936, 2025). "In their study, transferrin saturation (TSAT) <20% and serum iron ≤13 μmol/L were more strongly linked to congestion, reduced exercise capacity, and adverse outcomes than traditional ferritin-based definitions of iron deficiency." (PMID 40746303, 2025). "The protein extraction from cells for Western blot detection revealed a positive correlation between TF and HIF1 expression, suggesting that iron deficiency may contribute to the up-regulation of HIF-1 expression induced by oxidative stress." (PMID 38886644, 2024). "Absolute iron deficiency was defined as serum ferritin less than 30 ng/mL regardless of transferrin saturation." (PMID 39316402, 2024). "Using the three measures of iron deficiency, more depressed young adults, compared to non-depressed, had serum iron and transferrin deficiencies, although the differences were not statistically different." (PMID 38226328, 2024). "Iron status was categorised into five groups: iron deficiency anaemia (IDA), anaemia of chronic disease, IDA with anaemia of chronic disease, iron deficiency without anaemia, and iron replete based on haemoglobin, transferrin saturation, and ferritin levels." (PMID 39507475, 2024). "Iron deficiency in MS may involve variations in multiple genes, including TMPRSS6, HFE, TF, Dual Oxidase 2, CUBN, and SLC25A37." (PMID 38590521, 2024). "Obese adolescents in some regions, for instance, the prevalence of iron deficiency and iron deficiency anemia is notably higher than normal-weight counterparts, with a negative correlation between transferrin saturation and body mass index." (PMID 39159807, 2024). "A randomized controlled trial enrolled CKD patients (stages 3-5, not on dialysis) with iron deficiency anemia (hemoglobin ≤ 12 g/dL, ferritin ≤ 100 ng/mL, transferrin saturation ≤ 25%)." (PMID 39449947, 2024). "Iron, transferrin concentration, and % SAT negatively correlated with the left ventricular internal diameters normalized to body weight (LVIDdN), showing that the progression of MMVD is accompanied by slowly developing iron deficiency." (PMID 38762716, 2024). "Non-dialysis-dependent CKD patients (stage 3a-5) with iron deficiency with/without anemia (serum ferritin < 200 μg/L or transferrin saturation = 20% and serum ferritin 200-299 μg/L) were randomized to receive FDI or FCM in a 1:1 ratio." (PMID 38347520, 2024). "Intravenous iron therapy ameliorates iron parameters in patients with heart failure who present iron deficiency: serum ferritin <100 mg/L or 100–299 mg/L when transferrin saturation <20%, with or without cardiorenal syndrome or renal disease." (PMID 37374094, 2023). "Impaired iron transport (IIT) is a form of iron deficiency (ID) defined as transferrin saturation (TSAT) < 20% irrespective of serum ferritin levels." (PMID 37113703, 2023). "At baseline most patients had absolute iron deficiency (serum ferritin < 100 μg/L and transferrin saturation < 20%) as opposed to functional iron deficiency (61.5% vs. 38.5%)." (PMID 37884522, 2023). "In individuals with CKD and functional iron deficiency, TSAT, which reflects circulating iron, may be ≤20.0% because the bone marrow strips iron off the circulating transferrin faster than it can be replenished from the iron stores." (PMID 37415621, 2023).
iron deficiency (continued). "In iron-deficiency patients, serum levels of ferritin, transferrin saturation, and hepcidin were lower, while those of soluble transferrin receptor and transferrin were higher than in the non-iron deficiency patients." (PMID 36986182, 2023). "Lower iron conc., ferritin, transferrin saturation, TBIS, and hepcidin serum levels in association with higher levels of sTfR (nmol/L) were significantly (P = 0.001) reported in subjects with iron deficiency (ID) compared to those of normal iron status." (PMID 38102707, 2023). "In a study conducted on a group of over 2000 IBD patients, it was shown that there was no diagnostic threshold for ferritin or transferrin saturation providing sufficient sensitivity and specificity in the diagnosis of iron deficiency." (PMID 37048531, 2023). "The most common definition of iron deficiency applied was a serum ferritin <100 μg/L regardless of transferrin saturation (TSAT) or a TSAT <20% if ferritin was 100–300 μg/L." (PMID 36823953, 2023). "Unlike iron deficiency anemia wherein transferrin levels are increased, anemia of chronic diseases and anemia of mixed origin tend to show normal/low and low transferrin levels, respectively." (PMID 36214835, 2022). "In normal healthy individuals, iron deficiency (ID) is defined as transferrin saturation (TSAT) < 16% and serum ferritin < 30 μg/L, but in people with chronic kidney disease (CKD), defined thresholds for iron deficiency are higher (ferritin < 100 μg/L or TSAT < 20%), albeit this not evidence-based." (PMID 35896969, 2022). "In contrast, anemia (defined as Hb < 13 in males and < 12 in females, p = 0.225) and iron deficiency anemia (defined as anemia, ferritin < 10 ng/mL, transferrin saturation < 16%, p = 0.173) did not correlate significantly with H. pylori infection status." (PMID 36133500, 2022). "Of 2711 patients, 618 (22.8%) were iron deficient (= transferrin saturation [TSAT] < 16%) preoperatively, 173 (6.4% of the cohort) had an absolute iron deficiency (AID; TSAT < 16% and ferritin < 30 μg/L) and 445 (16.4%) had functional/mixed ID (TSAT < 16% and ferritin ≥ 30 μg/L)." (PMID 34427343, 2022). "Furthermore, infants with iron deficiency at 6 weeks, 6 months, and 12 months corrected age had comparable MCV and transferrin saturation values." (PMID 35807912, 2022). "In addition to decreased transferrin and increased ferritin, FID + CRA in patients with ovarian cancer was associated with older age and excessive weight compared to another type of iron deficiency (AID + IDA)." (PMID 36555993, 2022). "TSAT is calculated from serum iron and transferrin; a low TSAT value is an essential diagnostic criterion for iron deficiency, whether absolute or functional." (PMID 35956390, 2022). "During the development of cancer, the ferritin concentration increases, and the transferrin concentration decreases, often regardless of iron status, and iron deficiency can be diagnosed with ferritin values exceeding 50 μg/L." (PMID 36555993, 2022). "Serum transferrin is considered to be a relatively novel indicator of iron deficiency anemia as it has not been in use for diagnosis of iron deficiency anemia for long." (PMID 35844906, 2022). "Lastly, repeat ferritin and transferrin levels were not routinely performed in practice, so it is unclear if IV iron therapy successfully corrected iron deficiency in this cohort." (PMID 35807184, 2022). "Patients without iron deficiency were further sub-grouped as AI (serum ferritin >100 μg/L and transferrin saturation ≤ 20%) or other anemia etiology." (PMID 35895618, 2022). "As transferrin saturation is negatively associated with the iron demand in the body, increased transferrin saturation rules out iron deficiency in pre-eclampsia." (PMID 35959172, 2022). "Iron deficiency (as suggested by a low % transferrin saturation) was higher, though not significantly different, in females (34.4% vs. 23.3%, p = 0.17)." (PMID 33026590, 2021).